CD38 (CD38 molecule)
Diseases named in the same sentence as CD38 in open-access papers (continued):
Sharing a sentence is not in itself a finding about the gene and the disease.
infection (continued). "Eomesodermin (Eomes), a key transcription factor associated with the cytolytic activity of CD4+ T cells was expressed at similar levels by CD38+ and CD38- CD4+ T cells prior to infection." (PMID 27662621, 2016). "All volunteers in our CHMI study had a pre-existing proportion of CD4+ T cells expressing CD38 prior to infection, as do all healthy volunteers we have since examined." (PMID 27662621, 2016). "We have recently shown that the frequency of circulating CD38+ CD4+ T cells was significantly increased following experimental infection with P. falciparum and inversely correlated with parasite levels." (PMID 27930660, 2016). "Multivariate logistic regression showed a correlation of infection with a cluster containing %CD38+ Ki67− of CXCR5− CXCR3− CCR4+ TEM cells as the only positive coefficient with CD38 expression thus determining the significance." (PMID 27064238, 2016). "Peripheral blood CD8 T cells mounted a considerable response to TBEV-infection as assessed by Ki67 and CD38 co-expression." (PMID 25611738, 2015). "Regarding the percentage of activated CD4+ T-cells in blood, an upward trend was observed in agreement with a previous report of an increase in the density of CD38 on CD4+ cells in blood during early infection." (PMID 25465205, 2014). "Multiple studies using CD38 knockout mice have suggested that CD38/cADPR system plays important roles in neutrophils death by infection, autoimmune diabetes, and renal hemodynamics and excretory function." (PMID 24386592, 2013). "At six weeks post infection, LAINeffs∆-1 and LAINeffs∆-13 were determined to have 8.2 ± 3.5% (n = 4) and 6.1 ± 2.3% (n = 4) CD38+ HLA-DR+ double positive CD8+ T cells in blood, respectively." (PMID 24172637, 2013). "Recent studies have demonstrated that in primary HIV infection there is a strong correlation between higher DN T cell levels early in infection and lower HLADR+CD38+ CD8 T cells later in infection." (PMID 23825945, 2013). "We also observed greater frequencies of CD4 and CD8 T cells in the BAL fluid and blood samples that were both CD38+ and Ki67+ during the acute m3KOΔnef infection phase than in those animals infected with SIVmac239Δnef." (PMID 23785211, 2013). "We introduced human CD38 in the NAcc of CD38−/− sires using a lentiviral infection technique and examined the effects of local expression of CD38." (PMID 24059452, 2013). "Here we have shown that B cells with phenotypic characteristics of memory cells (CD19+IgD− CD38+, IgG1+) are generated in a primaryPlasmodium chabaudi chabaudi infection of mice." (PMID 19121080, 2009). "Chronic CD38 inhibition could potentially compromise immune surveillance or response to infections, particularly concerning in elderly populations who already face increased susceptibility to infections." (PMID 41542058, 2026). "Infection with L4 strains resulted in significantly higher percentages of CD38-positive CD4 T cells compared to L2 Beijing strains (median scaled frequencies 0.94 vs. 0.54, respectively), while L3 strains elicited intermediate responses (median scaled frequency 0.73)." (PMID 40162896, 2025). "To explore whether Cd38 mRNA induction during infection translates into increases in CD38 activity and protein expression in the brain, we assessed NADase activity and CD38 protein levels in the brains of ZIKV-infected mice." (PMID 41362627, 2025). "Consequently, prophylactic antiviral therapy, antibacterial agents, and vaccination against infections are advised prior to initiating anti-CD38-based therapy." (PMID 40786241, 2025). "The elevated expression of CD38 on CD4+ T-cells also is related to a poor prognosis in these subjects since it has been demonstrated that a decline important of CD4+ T-cells correspond to CD4+ CD38+ HLA-DR+ T-cell, moreover the loss of CD38+ CD4+ T-cells occurs in subjects with advanced infection." (PMID 40452022, 2025).
infection (continued). "Consequently, prophylactic antiviral therapy, antibacterial agents, and vaccination against infections are advised prior to initiating anti-CD38-based therapy (A1)." (PMID 40786241, 2025). "In this study, we found that lytic infection predominantly occurred in CD38+ cells." (PMID 40872823, 2025). "Similarly in the spleen, we found higher frequencies of CD25+PD‐1+ and PD‐1+ SFV‐specific CD8+ T cells in coinfection, but the proportion of CD38+KLRG1+ was higher in SFV‐only infection at 7 dpi." (PMID 39971320, 2025). "In addition, CD4+ T cells of IAV‐only infection in the brain had a higher frequency of single‐positive CD38+ cells than the SFV‐only and coinfection groups by 10 dpi." (PMID 39971320, 2025). "Notably, the two macaques in ART group that died from infection exhibited higher CD38 levels on their CD8+ T cells before death compared to other infected macaques." (PMID 40757099, 2025). "However, the study, in contrast to our findings, showed that CD38 deletion in LCMV-specific CD8+ T cells resulted in a modest but significant decrease in the frequency of TCF1+ Tpex cells during chronic LCMV Cl13 infection." (PMID 38451948, 2024). "The increased infection rate of MM patients undergoing anti-CD38 therapies is due to the CD38 expression on both malignant and healthy plasma cells and on other immune effector cells (e.g., NK cells), which leads to a reduction of polyclonal Igs and innate immune cell response." (PMID 39335161, 2024). "Transcriptional profiles of the genes CD38, Gpr18, Fpr2 (markers of classically activated macrophages), Arg1, and Egr2 (markers of alternatively activated macrophages) are significantly activated after infection with all viruses." (PMID 38473707, 2024). "We established a nomogram based on the T-cell count, CD28+CD8+ T-cell count, CD38+CD8+ T-cell count and clinical risk factors that can help clinical physicians quickly rule out IAC or identify elderly patients at greater risk for IAC at the onset of infection." (PMID 39726780, 2024). "It was proposed that infection with SARS-CoV-2 stimulates overexpression of CD38." (PMID 36675642, 2023). "Therefore, CD38 is considered to play a major part in potentiating an infection of SARS-CoV-2, as well as reacting to any secondary bacterial infections." (PMID 36675642, 2023). "To further verify whether CD38 was responsible for Daph inhibited inflammatory cytokines expression, we established an in vitro infection model of overexpressed CD38 by transfecting LPS-treated MLE-12 cells using the prokaryotic expression vector." (PMID 36998049, 2023). "In contrast, elevated frequencies of activated CD4+HLA-DR+CD38+ T cells were seen in the LE group when compared to the control and asymptomatic infection group (median values of 5.56%, 5.55%, and 7.13%, p = 0.0166 in uninfected control., W. bancrofti-infected, and LE, respectively)." (PMID 37375499, 2023). "This analysis revealed only very minor changes in circulating T cells at the peak of infection — a small increase in expression of CD38 on naive CD4+ T cells and the upregulation of T-bet in CD8+ terminally differentiated effector memory cells re-expressing CD45RA (Temra) and γδ T cells." (PMID 37616070, 2023). "Up-regulation of CD38 on monocytes during infection with listeria has been described previously." (PMID 36010615, 2022). "Conversely, patients that progressed to chronic HCV infection lacked this trend for declining frequencies and had uniformly high levels of CD38+ iNKT cells during the first year of infection (mean slope of linear regression, –0.028, with a 95% CI of –0.355 to 0.263)." (PMID 34905514, 2022). "Functionally, CD38 expression may need to be more tightly regulated upon infection resolution notably due to its role in regulating inflammation which activity has been linked to autoimmune disorders." (PMID 35492319, 2022).
infection (continued). "Interestingly, although the number of ROS-producing Ly6Chi monocytes decreased during infection with E. histolytica, the percentage of ROS+ CD38+ out of Ly6Chi monocytes increased rapidly, and remained elevated, during infection." (PMID 36010615, 2022). "Therefore, the mechanism comprises limiting the infection of host macrophages by affecting CD38 and regulating NAD+ metabolism." (PMID 35251964, 2022). "Nevertheless, on top of baseline immunosuppression, CD38 blockade may generally offer the potential for increased infection rates." (PMID 35395951, 2022). "CD38 is a multifunctional transmembrane protein that is widely expressed in immune cells, controls the innate immune response against infection, and closely relates to inflammatory pathways such as the Toll-like receptor (TLR) pathway and mitogen-activated protein kinase (MAPK) pathway." (PMID 33860064, 2021). "The preferential depletion of CD73+ CD4+ T cells in HIV-infection may be due to a combination of susceptibility to infection and a general recruitment of resting memory cells into the CD73-negative CD38+ pool." (PMID 33477692, 2021). "In vitro Puumala orthohantavirus infection of PBMC caused MAIT cell CD69 upregulation, and infection of MAIT cells in co-culture with the monocyte cell line THP-1 induced upregulation of CD69, CD38 and CD25, as well as the markers of cytolytic capacity perforin, granzyme B and CD107a." (PMID 35381137, 2021). "Although T cell activation markers such as HLA-DR and CD38 showed a higher expression tendency in the more severe group, especially early after infection (TP1), the difference in the frequency of activated CD4+ and CD8+ T cells between mild and more severely affected patients was not significant." (PMID 34867933, 2021). "In LCMV clone 13 infection, one TRM cell cluster expressing PD-1, CD38, CD39, CD54, and CXCR6 significantly associated with the liver, whereas a TEM cell subset of cells expressing high levels of PD-1, CX3CR1, NKG2A, and Ly6C (Cl13 cluster 5) was more abundant in the lungs and spleen." (PMID 33458613, 2021). "Indeed, we observed CD38+ memory B cells in the MLN at 10-days post-infection and the infection conferred a broadly protective response for 40 days." (PMID 34145279, 2021). "The NAD+ glycohydrolase CD38 is also important for controlling infections." (PMID 34871367, 2021). "Over the course of active infection there is a decline in activated CD8+CD38+HLA‐DR+ T cells." (PMID 33575657, 2021). "Given that there is a relationship between transitional (IgD+, CD38mid) and naïve (IgD+, CD38low, CD27-) it is possible that naïve B cells are acquiring increased CD38 expression as a result of the infection and culture process, and are thus falling into the transitional lineage gate at 3 dpi." (PMID 33075105, 2020). "CD38 is robustly induced during infection and the ensuing inflammation." (PMID 33329591, 2020). "Thus, the prominent expression of CD38 in immune cells suggests important roles in immune responses, ranging from the development of inflammation in response to infection to development or regulation of adaptive immune responses." (PMID 33329591, 2020). "Therefore, to further define functional changes in monocyte subsets during infection, we observed the expression of surface molecules CD38 and CD23." (PMID 33382687, 2020). "Furthermore, induction of CD38 expression in hematopoietic cells such as neutrophils, monocytes, dendritic cells, and macrophages is observed in response infection or cellular activation." (PMID 33329591, 2020). "To date, the impact of the absence of functional CD38 in the host response to infection has been studied using systemic CD38-deficient mice." (PMID 31963337, 2020). "Importantly, we defined a population of myeloid cells, primarily CD11cHi monocyte-derived cells, which expressed high levels of CD14, CD38, and Abca1, and had the highest infection rates and bacterial loads." (PMID 32544188, 2020).
infection (continued). "However, CD14 and CD38 single positive cells were also in the parenchyma; thus, location cannot account for the high infection rate of CD14+CD38+ cells." (PMID 32544188, 2020). "Although we reported a difference in the frequency of TB-specific IFN-γ+CD38+ and IFN-γ+HLA-DR+ CD4+ T cells in the TB/HCV group, we did not observe an association between the frequency of these cells and the outcome of infection or response to anti-TB therapy." (PMID 31952232, 2020). "To test our hypotheses, we observed the severity of kidney injury and examined inflammatory cytokine expression in WT and CD38−/− mice 2 hours post-LPS infection." (PMID 30915370, 2019). "TLR4 plays an essential role in promoting inflammatory response to LPS infection in CD38−/− mice." (PMID 30915370, 2019). "The inability of bacteria such as H. influenza to recycle or perform de novo synthesis of NAD+ may provide insight into the role of CD38 in response to infection." (PMID 31214171, 2019). "One exhaustion-inducing factor could perhaps be infection with a persistent virus; we therefore analyzed the expression of CD38 and HLA-DR on CD8+ T cells specific for persistent viruses." (PMID 29563914, 2018). "A higher CD38 expression on CD4+ T cells from viremic HIV-1-infected people is a biomarker of poor prognosis and is strongly associated with short survival in patients with advanced infection." (PMID 30083165, 2018). "Hence, it is possible that CD38 is required for other LXR-mediated activities beyond the control of infection." (PMID 29463868, 2018). "High CD38+PD-1+ expression was characteristic of one vaccinated individual prior to and early after vaccination, suggesting that the individual had some unidentified infection." (PMID 29483513, 2018). "In addition, patients undergoing primary infection displayed significantly higher frequencies of total plasma cells and of Ki67+ and Ki67+CD38+ expressing plasma cells compared to those who had experienced prior infection." (PMID 28700710, 2017). "Thus, we compared the frequencies of CD38+ T cells and B cells circulating before and after infection in P. falciparum or P. vivax infected volunteers." (PMID 27930660, 2016). "Although an increase in frequency of circulating CD38+ CD4+ T cells has been observed following immunization or infection in a number of host-pathogen systems, the role of those cells has not been elucidated, and impaired cytokine capacity has not been reported." (PMID 27662621, 2016). "However, post-infection, CD38+ CD8+ T cells had a greater expression of granzyme B and perforin compared to CD38- CD8+ T cells." (PMID 27930660, 2016). "Therefore, from day 50 on, the vast majority of the MSP1+ cells were CD38+GL7− MBCs that remained for at least 340 days post infection." (PMID 27473412, 2016). "Additionally, IL-4 has been found to enable productive infection of CD38+ T cells by X4-tropic HIV-1." (PMID 27064238, 2016). "Thus, we compared the changes in frequency of CD69+ and CD38+ T cells and B cells during infection with parasite burden, to determine if a certain cell type or phenotype was associated with parasite control." (PMID 27662621, 2016). "Immune senescence in HIV infection patients is clinically characterized by increased expression of CD38, apparently not directly caused by the infection." (PMID 26886066, 2016). "Similar to the CD38+ CD4+ T cells circulating in vivo in the P. falciparum experimental infection model, this in vitro generated CD38+ CD4+ T cell population showed a phenotype associated with recent activation and cytotoxic potential at both protein and mRNA levels." (PMID 27662621, 2016). "Finally, we investigated the cell subset precursor of the CD38+ CD4+ T cells that expanded in vivo upon infection." (PMID 27662621, 2016).
infection (continued). "We show that the levels of parasite burden following experimental P. falciparum blood-stage infection inversely correlated with the expansion of a specific subset of CD4+ T cells expressing CD38 and characterized by high cytotoxic potential but impaired cytokine production." (PMID 27662621, 2016). "However, a trend for an increase in Eomes expression in CD38+ CD4+ T cells following infection was observed." (PMID 27662621, 2016). "However, an inverse correlation between the frequency of CD38+ T cells and B cells and parasite burden during infection was apparent." (PMID 27662621, 2016). "Peripheral blood CD8 T cells were activated (determined by Ki67 and CD38 expression) in response to infection and expressed perforin, granzyme B, HLA-DR, PD-1, T-bet and Eomes together with low levels of Bcl-2 at day 7 after hospitalization, phenotypically defining these as effector cells." (PMID 25611738, 2015). "However, the frequency of lung CD38+ increased from day 6 to 14 post infection, whereas CD138+ cells increased significantly at 6 days post infection, and then dropped to normal level later until day 14 post infection." (PMID 24666970, 2014). "There were significantly more CD38+ cells in the minor and severe infection groups than in the healthy and silent infection groups among CD8+ cells (CD4+: 5.13 and 9.14 vs. 1.67 and 2.49, respectively, p < 0.001; CD8+: 4.28 and 12.90 vs. 1.03 and 0.75, respectively, p < 0.001)." (PMID 24646014, 2014). "IgG replacement therapy leads to reduced expression of Ki67, CD38, and HLA-DR on CD8 T cells, indicating that IgG replacement may help control infections or infection-associated factors that are implicated in chronic activation of the CD8 T cells." (PMID 25566250, 2014). "In addition, the activation marker CD38 dropped during the course of infection in all pentamer-positive CD8+ T cells in patient 1 despite a high variability in sequence and viral load during this phase." (PMID 24073713, 2013). "Future studies may be directed towards understanding the role of CD38 in response to infection and thus its role in HAND." (PMID 22027397, 2011). "There were marginal increases in CD38 and HLA-DR expression in response to infection." (PMID 18923697, 2008). "CD38 has important roles in immune function and calcium signaling and chronic inhibition could have unintended consequences, particularly in the context of infection or injury." (PMID 41542058, 2026). "Furthermore, total ICs exhibited significantly lower levels on activated (HLA-DR+/CD38+) CD4+ T cells during the chronic phase (133 days post-infection) and on activated CD8+ T cells during the acute and chronic infection phases (49, 84, and 133 days post-infection) in ECs." (PMID 40637373, 2025). "Through understanding the underlying molecular mechanisms and the broader immune context driving the distinct responses of CD38+ and CD38− AMs to Mtb infection, we could guide the screening of therapeutics aimed at improving macrophage control of Mtb early in infection." (PMID 39070650, 2024). "Finally, we found an uneven increase of a CD38+ myeloid cell (CD11b+, CD11clo) population and of various types of DCs post-infection, suggesting that although frequencies of myeloid cells are similar in every case, their activation status and functionality changed over time." (PMID 37539049, 2023). "Cluster of differentiation 38 (CD38) is a multifunctional type II transmembrane glycoprotein widely expressed on the surface of various immunocytes membranes that mediates host immune response to infection and plays an important role in many inflammatory diseases." (PMID 36998049, 2023). "This difference may be due to the different duration and site of antigen contact and different inflammatory responses after vaccination and infection, as indicated by lower CD38 expression on specific CD8+ early memory T cells after vaccination compared to natural infection." (PMID 35214700, 2022).